RPA1 (replication protein A1)
Diseases named in the same sentence as RPA1 in open-access papers (continued):
Sharing a sentence is not in itself a finding about the gene and the disease.
B-cell lymphoma (5 papers, 2020 to 2022). "For example, a 3′tRF named CU1276 (tRF‐3027b) binds 3′UTR of RPA1 to suppress its expressions in an Argonaute‐dependent, miRNA‐fashion and regulate responses to DNA damage in B cell lymphoma." (PMID 35957621, 2022). "CU1276 is one of the first tsRNAs reported to bind target genes through seed sequences; CU1276 was found to bind to the 3′ UTR of RPA1, thus inhibiting its expression and consequently the proliferation of B-cell lymphoma cells." (PMID 36388094, 2022). "In B-cell lymphomas, low expression of tRF-3 CU1276 could modulate the molecular response to cellular DNA damage and inhibit cell proliferation by targeting replication protein A1(RPA1)." (PMID 35658952, 2022).
colorectal cancer (5 papers, 2020 to 2025). A primary or metastatic malignant neoplasm that affects the colon or rectum. "For example, a recent report showed that RPA1 (ranked 8th in patient TCGA-E2-A15M) works as a presumed oncogene in tumorigenesis and serves as a prognosticative biomarker for colorectal cancer." (PMID 38254011, 2024). "Rs5030740 was located in the 3′-UTR of RPA1, which is carrying C allele markedly associated with poor DCR and prognosis compared to those with the T allele in colorectal cancer." (PMID 36277983, 2022). "In addition, expression of RPA1 has shown markedly correlated with lymphoid tumors and colorectal cancer." (PMID 36277983, 2022).
gastric cancer (5 papers, 2018 to 2023). A primary or metastatic malignant neoplasm involving the stomach. "In human gastric cancer tissues, the mRNA and protein expression levels of NKX6.3 and RPA1 were significantly reduced, whereas CDT1 were markedly increased." (PMID 34893582, 2021). "Additionally, the expression of NKX6.3 shows a strong inverse correlation with CDT1 and a strong positive correlation with RPA1 in tumors derived from mice implanted with HFE-145shNKX6.3#1 and HFE-145shNKX6.3#2 cells and human gastric cancer tissues." (PMID 34893582, 2021). "All the three subunits RPA1, RPA2, and RPA3, were more abundant (with statistical significance evidence) in lymph node negative and earlier stage (stage I and II) gastric carcinomas." (PMID 36177351, 2022).
cervical cancer (4 papers, 2009 to 2020). A primary or metastatic malignant neoplasm involving the cervix. "Interestingly, we observed that FEN1, PCNA, RAD51 and RPA1 protein levels were upregulated in cervical cancer derived cell lines as well as in keratinocytes transduced with HPV16 oncogenes when compared to normal PHK." (PMID 30674977, 2019).
glioma (4 papers, 2020 to 2023). A benign or malignant brain and spinal cord tumor that arises from glial cells (astrocytes, oligodendrocytes, ependymal cells). "We found comparable frequency of cases with RPA1 variants across solid tumors (n = 22, 1.1%), CNS cancers (n = 12, 1.1%) and hematological malignancies (n = 29, 0.8%)." (PMID 37869077, 2023). "Furthermore, 4 cases with high grade glioma harbored 3 RPA1 variants (n = 1 novel, n = 1 ultra-rare), all clustering within DBD-C domain of RPA1." (PMID 37869077, 2023).
hepatocellular carcinoma (4 papers, 2019 to 2024). A malignant tumor that arises from hepatocytes. "A tissue array confirmed elevated RPA1 expression and enhanced nuclear localization in primary hepatocellular carcinoma samples." (PMID 39660144, 2024). "A study in hepatocellular carcinoma showed that CDC20 and Rfc4 are involved in cancer cell survival, and another study showed that Rfc4 interacts with RPA1 for DNA replication and DNA damage repair." (PMID 39125953, 2024). "With a cutoff score of eight, 68.2% of the hepatocellular carcinoma samples exhibited high RPA1 expression, while none of the adjacent liver tissues showed high expression (p<0.001)." (PMID 39660144, 2024).
bladder cancer (3 papers, 2014 to 2022). "In this study, we investigated the mRNA expression of 9 genes (XPB to XPG, ERCC1, RPA1, RPA2)involved in the NER pathway in bladder cancer tissues with/without recurrence, compared with normal bladder cancer tissue." (PMID 25535740, 2014).
Miller-Dieker syndrome (3 papers, 2010 to 2015). "Thus, haploinsufficiency of replication protein A1 (RPA1) and replication factor C2 (RFC2) has been associated with the Miller-Dieker lissencephaly syndrome (MIM #247200) and the William-Beuren syndrome (MIM #194050), respectively." (PMID 21054854, 2010). "Previously, we have shown that Miller-Dieker Syndrome (MDS) and severe Isolated Lissencephaly Sequence (ILS+) patient-derived LBLs with RPA1 haploinsufficiency fail to activate the ATR-dependent G2-M checkpoint." (PMID 21901111, 2011).
autoimmune disease (2 papers, 2006 to 2023). A disorder resulting from loss of function or tissue destruction of an organ or multiple organs, arising from humoral or cellular immune responses of the individual to their own tissue constituents. "Conversely, depletion of T cell‐intrinsic RPA1 results in lymphopenia and increases susceptibility to autoimmune disease through inducing T cell necroptosis." (PMID 36721037, 2023). "Through TBK1‐IRF3 and RIPK3‐MLKL signaling, RPA1 deficiency initiated necroptotic cell death on recent thymic emigrants and proliferative T cells, consequently resulting in lymphopenia and increased susceptibility to autoimmune diseases." (PMID 36721037, 2023). "Conversely, blockade of T cell necroptosis by RIPK3 inhibitor largely ameliorated the inflammatory damage induced by RPA1 depletion, which further confirm the importance of T cell necroptosis in the pathogenesis of autoimmune disorders." (PMID 36721037, 2023).
hypopharyngeal cancer (2 papers, 2021 to 2024). Carcinoma, predominantly squamous cell, arising from the epithelial cells of the hypopharynx. "Targeting RPA1 by shRNAs in radioresistant hypopharyngeal cancer cell." (PMID 34900673, 2021).
liver cancer (2 papers, 2020 to 2024). An epithelial or non-epithelial malignant neoplasm that arises from the liver. "UALCAN analysis indicated a preferential up-regulation of ETAA1 and RPA1 in advanced liver cancer stages and in poorly differentiated tumor grades, when compared to normal tissue controls." (PMID 39660144, 2024). "Another study reported that RPA1 was increased in both liver cancer cell lines and HCC tissues and promoted the proliferation of HCC via the cyclin-dependent-kinase 4(CDK4)/cyclin-D pathway." (PMID 32552682, 2020). "Furthermore, we explored the clinicopathologic characteristics of RPA1-dependent, ETAA1-mediated events in liver cancer patients by analyzing the correlations between ETAA1 and RPA1 expression levels and liver cancer stages and tumor grades." (PMID 39660144, 2024).
non-small cell lung carcinoma (2 papers, 2021 to 2026). A group of at least three distinct histological types of lung cancer, including non-small cell squamous cell carcinoma, adenocarcinoma, and large cell carcinoma. "In addition, NRF2 negatively regulates FOCAD gene expression in human non-small-cell lung cancer (NSCLC) cells, which is dependent on the NRF2-replication protein A1 (RPA1)-ARE complex." (PMID 35118067, 2021).
sarcoma (2 papers, 2023). A usually aggressive malignant neoplasm of the soft tissue or bone. "Among solid tumor cases with RPA1 variants, 31.8% (7/22) presented with sarcomas and 27.3% (6/22) were diagnosed with neuroblastoma." (PMID 37869077, 2023). "Notably, the 7 sarcoma cases carried 6 unique RPA1 variants (n = 2 novel and n = 1 ultra-rare) and only one was noted to have a concomitant germline mutation." (PMID 37869077, 2023).
Sepsis (2 papers, 2025). Sepsis is defined as life-threatening organ dysfunction caused by a dysregulated host response to infection. "Consistently, IGV browser visualization demonstrated reduced m6A modification levels and decreased RPA1 expression in PBMCs from the non-survivor group compared to survivors, further supporting RPA1 as a putative m6A-regulated target gene in sepsis." (PMID 40625751, 2025). "The identification of the key target gene RPA1 offers new insights into the immunopathological mechanisms of sepsis and lays a theoretical foundation for future precision interventions and therapeutic strategies." (PMID 40625751, 2025). "A total of six hub genes (RORA, L3MBTL2, PHC1, RPA1, CHD3, and RANGAP1) associated with SUMOylation was identified in sepsis in the current study." (PMID 40274894, 2025). "However, the specific role of RPA1 within the platelet-immune regulatory network in sepsis remains largely unexplored and lacks direct experimental evidence." (PMID 40625751, 2025). "Additionally, the APP → CD74 signaling axis and the RPA1-centered regulatory network warrant in-depth experimental exploration to evaluate their potential as targets for therapeutic intervention in sepsis." (PMID 40625751, 2025). "Moreover, RPA1, identified as a candidate gene at the intersection of differential m6A modification and platelet-specific expression, may play a key role in platelet immune function and the epigenetic regulation of sepsis." (PMID 40625751, 2025). "Furthermore, the integration of advanced technologies such as CRISPR-based gene editing, single-cell multi-omics, and high-throughput epigenomic profiling may offer deeper mechanistic insights into the role of RPA1 in platelet-mediated immune regulation and sepsis progression." (PMID 40625751, 2025). "This study shows that hub genes (RORA, L3MBTL2, PHC1, RPA1, CHD3, and RANGAP1) may distinguish controls and diseases to facilitate diagnosis of sepsis." (PMID 40274894, 2025). "L3MBTL2, RPA1, and RANGAP1 have not been previously associated with sepsis, offering new avenues to explore their roles." (PMID 40274894, 2025).
ulcerative colitis (2 papers, 2023 to 2025). An inflammatory bowel disease involving the mucosal surface of the large intestine and rectum. "In addition, aberrant expression of RPA1 has been implicated in various pathological conditions, including ulcerative colitis, lipid metabolism disorders, radioresistant cancers, and neurodegenerative diseases." (PMID 40625751, 2025). "Our present study reports that RPA1 transcription is downregulated in patients with ulcerative colitis." (PMID 36721037, 2023). "Clinical analysis reveals that the expression of RPA1 is reduced in patients with ulcerative colitis or other autoinflammatory diseases." (PMID 36721037, 2023).
African trypanosomiasis (1 paper, 2023). "Using structural modeling, we discover an inhibitor, JC-229, that targets RPA1 in Trypanosoma brucei, the causative parasite of African trypanosomiasis." (PMID 37474515, 2023).
anemia (1 paper, 2017). A reduction in the number of red blood cells, the amount of hemoglobin, and/or the volume of packed red blood cells. "Polymorphisms in GTF2H1, ERCC2 and RPA1 showed significant association with anemia." (PMID 28924235, 2017).
angiosarcoma (1 paper, 2023). A malignant tumor arising from the endothelial cells of the blood vessels. "EME1, FANCA, RAD51, TP53BP1, RAD51C, RPA1, and XRCC2 exhibited alterations in more than half the cases of the angiosarcoma cohort." (PMID 36779660, 2023).
autoimmune hepatitis (1 paper, 2023). Hepatitis caused by autoantibodies. "To explore whether T cell‐specific depletion of Rpa1 can exacerbate other inflammatory disease, we employed concanavalin A (Con A)‐induced autoimmune hepatitis mice model." (PMID 36721037, 2023).
bone marrow failure (1 paper, 2023). "Besides these descriptions associating germline RPA1 variants with bone marrow failure or hematologic malignancies, the RPA2 or RPA3 genes have not been linked to any human diseases thus far." (PMID 37869077, 2023).
Burkitt lymphoma (1 paper, 2019). A rare form of malignant mature B-cell non-Hodgkin lymphoma. "Similar to canonical miRNAs, CU1276 represses the expression of replication protein A1 (RPA1), an activity that is crucial for DNA-damage repair, thereby inhibiting the outgrowth of Burkitt’s lymphoma cells." (PMID 31752361, 2019).
colitis (1 paper, 2023). Inflammation of the colon. "Accordingly, T cell‐intrinsic Rpa1 depletion mice exhibit increased susceptibility to experimental colitis or hepatitis." (PMID 36721037, 2023). "Here, we found downregulation of RPA1 in PMBCs from colitis patients." (PMID 36721037, 2023).
colon adenocarcinoma (1 paper, 2023). "Finally, survival analysis by cBioPortal demonstrated that higher mRNA expression of RPA1 correlated with shorter median overall survival of BRAFV600E-mutated patients with colon adenocarcinoma and mucinous adenocarcinoma of the colon." (PMID 37106808, 2023). "Importantly, our in silico analysis also showed that increased RPA1 expression at the gene level was correlated with poor survival outcomes in BRAFV600E-mutated patients with colon adenocarcinoma and mucinous adenocarcinoma of the colon." (PMID 37106808, 2023).
dyskeratosis congenita (1 paper, 2023). Dyskeratosis congenita (DC) is a rare ectodermal dysplasia that often presents with the classic triad of nail dysplasia, skin pigmentary changes, and oral leukoplakia associated with a high risk of bone marrow failure (BMF) and cancer. "Germline pathogenic variants affecting RPA1 were recently described in patients with Telomere Biology Disorders (TBD), also known as dyskeratosis congenita or short telomere syndrome." (PMID 37869077, 2023).
ependymoma (1 paper, 2023). A WHO grade II, slow growing tumor of children and young adults, usually located intraventricularly. "High protein folding scores were found for 4 unique RPA1 variants in 4 cases, 3 identified in patients with B-ALL and one in a patient with ependymoma." (PMID 37869077, 2023).
fatty liver (1 paper, 2024). "The loss of RPA1 promoted occurrence of hepatic steatosis, fatty liver, and even spontaneous HCC." (PMID 39627201, 2024).
inflammatory bowel disease (1 paper, 2023). A spectrum of small and large bowel inflammatory diseases of unknown etiology. "To determine the involvement of RPA1 in the pathogenesis of inflammatory bowel disease, we employed dextran sulphate sodium (DSS)‐induced acute colitis mouse model." (PMID 36721037, 2023).
invasive breast carcinoma (1 paper, 2023). A carcinoma that infiltrates the breast parenchyma. "Whereas normal breast tissues have high levels of RPA1 expression, the nuclear RPA3 level was significantly reduced in DCIS and invasive breast cancers (P < 0.0001)." (PMID 36997566, 2023). "We first immunohistochemically profiled RPA1, 2 and 3 in a cohort of 776 pure DCIS, 239 DCIS that co-exist with invasive breast cancer (IBC), 50 normal breast tissue and 4221 IBC." (PMID 36997566, 2023). "Whereas normal breast tissues have high levels of RPA1 protein expression, the RPA1 level was significantly reduced in DCIS and invasive breast cancers (P < 0.0001)." (PMID 36997566, 2023).
lymphoid tumor (1 paper, 2024). "As a crucial member of this complex, RPA1, when dysfunctional, can lead to genomic instability and the development of lymphoid tumor." (PMID 39660144, 2024).
lymphopenia (1 paper, 2023). Reduction in the number of lymphocytes. "Utilizing T cell‐specific Rpa1‐deficient (Rpa1fl/fl Cd4‐cre) mice, loss of Rpa1 results in lymphopenia through restraining peripheral T cell population and limiting TCR repertoire diversity." (PMID 36721037, 2023). "Taken together, our data demonstrate that loss of RPA1 leads to lymphopenia through triggering T cell necroptosis." (PMID 36721037, 2023). "To determine whether T cell necroptosis is the main cause for the lymphopenia induced by RPA1 deficiency, we crossed the CKO mice (CD4creRpa1fl/fl) with Ripk3−/− mice and generated the CD4creRpa1fl/fl Ripk3−/− mice." (PMID 36721037, 2023). "Above all, our data uncover that deletion of RPA1 restricts peripheral T cell population and leads to lymphopenia." (PMID 36721037, 2023).
Lynch syndrome (1 paper, 2013). An autosomal dominant hereditary neoplastic syndrome characterized by the development of colorectal carcinoma and a high risk of developing endometrial carcinoma, gastric carcinoma, ovarian carcinoma, renal pelvis carcinoma, and small intestinal carcinoma. "Lynch syndrome tumors showed up-regulation of 1129 genes, e.g. genes involved in G1/S transition (CCNE, CCNH, E2F2 and CDK2), DNA replication (CDC45, RPA1, RFC5, MCM4 and POLD3) and chromosomal organization and mitosis (CCNB2, MLF1IP, CASC5, KIF2C and PLK4), which is in line with previous findings." (PMID 23951239, 2013).
medulloblastoma (1 paper, 2023). A malignant, invasive embryonal neoplasm arising from the cerebellum. "Among cases with CNS tumors, 4 patients with medulloblastoma harbored novel (n = 3) or ultra-rare (n = 1) RPA1 variants." (PMID 37869077, 2023). "Interestingly, 3 of the 5 medulloblastoma cases had novel and one very rare germline RPA1, as well as one ultra-rare RPA3 variant." (PMID 37869077, 2023).
myelodysplastic syndrome (1 paper, 2023). A clonal hematopoietic disorder characterized by dysplasia and ineffective hematopoiesis in one or more of the hematopoietic cell lines. "Because germline RPA1 mutations are linked to early onset TBD with predisposition to myelodysplastic syndromes, we interrogated pediatric cancer cohorts to define the prevalence and spectrum of rare/novel and putative damaging germline RPA1, RPA2, and RPA3 variants." (PMID 37869077, 2023).
neuroblastoma (1 paper, 2023). Neuroblastoma (NB) is the most common solid, extracranial childhood tumor.
neutropenia (1 paper, 2017). A decrease in the number of neutrophils found in the blood. "Subgroup analyses in the age of patients ≤ 58 showed that DDB2 and RPA1 presented consecutive significant signals on neutropenia." (PMID 28924235, 2017). "Polymorphisms in ERCC2, ERCC6, DDB2, RPA1, POLD1 and POLD3 presented significant association with neutropenia." (PMID 28924235, 2017).
ovarian tumours (1 paper, 2026). "We evaluated RPA1, 2, and 3 sub-units protein expression in 331 ovarian tumours, transcripts in 1287 tumours and bioinformatics in the ovarian TCGA cohort (n = 379)." (PMID 41702233, 2026).
retinoblastoma (1 paper, 2023). A malignant tumor that originates in the nuclear layer of the retina. "Three cases of retinoblastoma harbored unique RPA1 variants (2 ultra-rare) with 2 cases having concomitant germline RB1 mutation." (PMID 37869077, 2023).
serous ovarian cancers (1 paper, 2026). "High nuclear RPA1 and RPA2 protein was significantly associated with high grade serous ovarian cancers (HGSOC), advanced stage, platinum resistance and worse progression free survival (PFS) (all ps <0.05)." (PMID 41702233, 2026).
Thrombocytopenia (1 paper, 2017). A reduction in the number of circulating thrombocytes. "Subgroup analyses in different histological types showed that rs3786136 in RPA1 were significantly associated with thrombocytopenia in SCC (χ2 test P = 3.13 × 10−5; OR = 4.71, 95%CI:1.10–20.12, P = 0.037) after Bonferroni correction." (PMID 28924235, 2017). "Polymorphisms in RPA1 showed significant association with thrombocytopenia." (PMID 28924235, 2017). "RPA1 and POLD1 presented consecutive significant signals on thrombocytopenia." (PMID 28924235, 2017).
Wilms tumor (1 paper, 2023). An embryonal neoplasm characterized by the presence of epithelial, mesenchymal, and blastema components. "Two cases of Wilms tumor were identified to have germline RPA1 variants." (PMID 37869077, 2023).